KRTAP5-11 (keratin associated protein 5-11)
Description:
In the hair cortex, hair keratin intermediate filaments are embedded in an interfilamentous matrix, consisting of hair keratin-associated protein (KRTAP), which are essential for the formation of a rigid and resistant hair shaft through their extensive disulfide bond cross-linking with abundant cysteine residues of hair keratins. The matrix proteins include the high-sulfur and high-glycine-tyrosine keratins.
Synonyms: KRTAP5.11; KRTAP5-6
Tractability: No criterion of Open Targets' tractability assessment is met for any kind of drug.
Gene: Protein-coding gene on chromosome 11 (71,581,855 to 71,603,353, reverse strand). Ensembl gene ENSG00000204571.
Pathways (Reactome):
Developmental Biology: Keratinization
Gene Ontology:
Molecular function: protein binding
Cellular component: cytosol; keratin filament
Genetic constraint (gnomAD): Loss-of-function variants: 4 observed, 2.82 expected, observed/expected ratio (o/e) 1.42, 90% interval 0.62 to 1.92. That is too few expected variants to judge how well the gene tolerates losing a copy. Missense variants: 202 observed, 196.52 expected, observed/expected ratio (o/e) 1.03, 90% interval 0.92 to 1.15. Synonymous variants: 88 observed, 75.02 expected, observed/expected ratio (o/e) 1.17, 90% interval 0.99 to 1.4.